CD4 (CD4 molecule)
Diseases named in the same sentence as CD4 in open-access papers (continued):
Sharing a sentence is not in itself a finding about the gene and the disease.
Hodgkins lymphoma (continued). "In summary, this study showed that there was a CD4 count decline in the 12 months prior to diagnosis of Hodgkin lymphoma among HIV-infected individuals who were fully virologically suppressed and in receipt of HAART." (PMID 24504076, 2014). "Of note, an individual’s CD4 count at NADC diagnosis remains a strong predictor of subsequent mortality for all NADC combined (as well as for Hodgkin’s lymphoma), emphasising the need for continued use of cART, even in those with NADC." (PMID 24106926, 2013). "In a cohort of Hodgkins lymphoma patients, an argument was made by Marshall and colleagues for a contributory role of CD4+ IL-10+ Tr1 cells toward ineffective clearance of Hodgkins lymphoma." (PMID 23874336, 2013). "MC and LD subtypes of classical HL are correlated with more advanced immune compromise, while nodular sclerosis (NS) histology increases with higher CD4 counts and use of cART." (PMID 22272202, 2012). "On the contrary, the 10-year survival of patients with Hodgkin lymphoma was significantly longer if the CD4 TIL infiltrate contains a higher frequency of c-Maf cells, which should produce IL-4 and be considered as Th2." (PMID 24212939, 2011). "Decreased CD3+ and CD4+ T cells and increased IgE levels were more frequently observed in the Hodgkin’s disease survivors with recurrent infections." (PMID 21245613, 2010). "Corresponding article: Hernandez O, Oweity T, Ibrahim S: Is an Increase in CD4/CD8 T-cell ratio in lymph node fine needle aspiration helpful for diagnosing Hodgkin lymphoma?" (PMID 16150141, 2005). "Using flow cytometry, a recent study shown an increase in CD4/CD8 T-cell ratio (range 3.9 to 28 with average of 11.2) in lymph nodes of patients with classical Hodgkin lymphoma." (PMID 16153296, 2005). "Most PWH develop Hodgkin lymphoma after ART initiation, and it has been hypothesized that the ART-induced repopulation of CD4 cells may provide a favorable microenvironment for the activation of Hodgkin lymphoma–specific Reed-Sternberg cells." (PMID 39736138, 2025). "Aberrantly expressing CD4 positive nodular sclerosis subtype classical Hodgkin lymphoma patients at baseline may be candidates for frontline brentuximab vedotin administration, if verified in large clinical trials." (PMID 27429620, 2016). "The authors of that study proposed monitoring of CD4 counts and that a declining CD4 count might alert clinicians to the possibility of Hodgkin lymphoma." (PMID 24504076, 2014). "Median CD4 count at diagnosis of Hodgkin lymphoma was 270 cells/μl (IQR 153–368)." (PMID 24504076, 2014). "Importantly, low CD4+ T-cell count at NADC diagnosis was strongly associated with poor survival for all NADC combined and in particular for Hodgkin lymphoma, emphasizing the need for timely HIV treatment." (PMID 24760049, 2014). "In this respect, Hodgkin lymphoma infiltrating lymphocytes have been shown to contain large populations of both Tr1 and CD4+CD25+ regulatory T cells, and it would be interesting to see whether a similar situation occurs in NPC." (PMID 15450122, 2004). "Importantly, CT-treated Hodgkin lymphoma (HL) patients, with reduced B cell percentages but with intact CD4 + T cells phenotypes, still able to retain antibody responses, suggesting a critical role for CD4 + T cells in supporting antiviral humoral immunity." (PMID 40630518, 2025). "Therefore the observed fall in CD4 count in patients with Hodgkin lymphoma cannot be ascribed to drugs that might have suppressed their CD4 counts." (PMID 24504076, 2014). "For example, the attributable fraction of EBV-associated Hodgkin lymphoma in the general population is 20-50%, but in HIV-infected patients, 75%-100% of Hodgkin lymphoma is attributable to EBV, possibly due to aberrant CD4 T-cell responses to EBV infection." (PMID 40909339, 2025). "Hodgkin lymphoma exposed to anti-PD-1 correlated in tumor microenvironment with an immune depletion of CD8+ T lymphocytes and overexpression of LAG-3 on CD4+ helper T lymphocytes." (PMID 34771650, 2021).
Hodgkins lymphoma (continued). "In the COHERE study patients with Hodgkin lymphoma and who were in receipt of HAART lost 98 CD4 lymphocytes (95% CI, −159 to −36 cells) in the year preceding diagnosis whilst maintaining viral suppression on HAART." (PMID 24504076, 2014). "A review of classic Hodgkin's lymphoma showed that approximately 5% (12 of 259 cases) expressed at least one T-cell marker in the following order: CD2, CD4, CD3, CD5, and CD8." (PMID 23738160, 2013). "CD4/CD8 T-cell ratio comparisons are made with cytomorphological diagnoses of reactive, atypical, non-Hodgkin lymphoma, and Hodgkin lymphoma cases." (PMID 16336672, 2005). "In 85 cases with increased CD4/CD8 T-cell ratio, only 7 cases were proven, using tissue sections, to be Hodgkin lymphoma with one additional case called by cytology (9%)." (PMID 16153296, 2005). "CD4/CD8 T-cell ratio comparisons are made with cytomorphologic diagnoses of reactive, atypical, non-Hodgkin lymphoma, and Hodgkin lymphoma cases." (PMID 16150141, 2005). "Our study suggests that anti-PD-1 immunotherapy-resistant Hodgkin lymphoma could correlate in tumor microenvironment with an immune depletion of CD8+ T lymphocytes and overexpression of LAG-3 on CD4+ helper T lymphocytes." (PMID 34771650, 2021). "An association between a falling CD4 cell count, not explained by virological failure of HAART, and a diagnosis of Hodgkin lymphoma has been described by the COHERE collaboration." (PMID 24504076, 2014). "In this study we investigated the value of an increased CD4/CD8 ratio (≥4), in otherwise non-diagnostic flow cytometry findings, as a diagnostic marker for Hodgkin lymphoma in FNA biopsies." (PMID 16153296, 2005). "EBNA1-specific CD4+ T lymphocytes seem to have an important protective role in vivo, as inferred by their reduction or absence in PTLD patients, in some pediatric forms of BL, in EBV-related Hodgkin lymphoma, in NHL that develop in HIV patients, and in central nervous system lymphomas." (PMID 28289418, 2017). "A recent study on Hodgkin’s disease and anaplastic large cell lymphoma reported that tumor cells may aberrantly express TNF-α or thymus- and activation-regulated chemokines (TARC), which might attract a specific lymphocytic subset and CD4 + T-cell with a Th2 phenotype in particular." (PMID 31960941, 2020).
Hyperglycemia (60 papers, 2009 to 2026). An increased concentration of glucose in the blood. "Overall, we found that hyperglycemia is associated with poor health outcomes, and changes in cytokine levels, altered counts and functioning of dendritic cells, monocytes, and CD4+ T cells in patients with DM-TB." (PMID 39981106, 2024). "Some studies have associated hyperglycemia with higher numbers of peripheral CD4+ T-cells, and higher Th1 and Th17 subset frequencies." (PMID 38794641, 2024). "Multivariate analysis of the association of hyperglycemia with all-cause and cause-specific mortality by baseline CD4 cell count (n = 2914)." (PMID 36301817, 2022). "Hyperglycemia in T2D is hypothesized to cause increased peripheral CD4+ T-cell flux, aberrant activation and effector functions, and impaired migration." (PMID 38794641, 2024). "The evidence showed hyperglycemia to be associated with unfavorable treatment outcomes; altered counts and functioning of dendritic cells, monocytes, and CD4+ T cells; and changes in cytokine levels (mainly INF-γ, IL-17, IL-1β, IL-2, IL-6, IL-10, and TNF-α) in patients with DM-TB." (PMID 39981106, 2024). "In sensitivity analysis, hyperglycemia was associated with increased hazards of all-cause mortality in both people with CD4 count <200 cells/mm3 (HR: 2.02, 95% CI: 1.47–2.78, p<0.0001) and CD4 count ≥200 cells/mm3 (HR: 3.26, 95% CI: 1.96–5.42, p<0.0001)." (PMID 36301817, 2022). "In addition, one clinical study reported an increase of CD4+Foxp3+CD39+ Treg cells in PBMCs from overweight T2DM patients associated with hyperglycemia, and we observed an elevated level of CD39 among T cells, B cells, and monocytes." (PMID 36686486, 2022). "Another potential reason that DN T cells in the blood spike more intensely prior to hyperglycemia is that they are removed locally from the pancreas more than CD4 + T cells to block these protective effects." (PMID 40106422, 2025). "When tested, all patients were in euglycemic conditions, bearing in mind that hyperglycemia can influence the quantity of CD4+ T cells." (PMID 39876913, 2024). "Simultaneously, it was observed that hyperglycaemia significantly increases the ratio of helper CD4+ T cells to all CD4+ T cells (from 4.5 to 8.5%) in peripheral blood." (PMID 39273582, 2024). "At 8 weeks post-immunization (7 weeks post-transplantation), IMM-RIP-B7.1 mice which already had developed severe insulitis and hyperglycemia displayed the highest increase of CD11b+ myeloid cells, CD4+ and CD8+ T Cells and CD19+ B Cells." (PMID 36875761, 2023). "The pathophysiological mechanisms responsible for non-cirrhotic NAFLD-HCC onset include systemic inflammation, hyperglycemia, IR, and the immune dysregulation with low intrahepatic CD4+ T lymphocytes." (PMID 36831120, 2023). "Our results showed that female patients, those with hyperglycemia, and patients with baseline CD4+ T-cell count >500 cells/μL had a higher prevalence of hyperlipidemia, with rates of 37.0%, 49.0%, and 41.3%, respectively." (PMID 35929632, 2022). "Female patients, those with hyperglycemia, and patients with CD4+ cell counts >500 cells/μL had a higher prevalence of hyperlipidemia with 37.0%, 49.0%, and 41.3%, respectively." (PMID 35929632, 2022). "For example, hyperglycemia can promote the senescence of CD4 + and CD8 + T cells, resulting in reduced immunity of the B cells." (PMID 36229890, 2022). "As compared to normal CD4 T cells primed by dendritic cells, these hyperglycemia-activated CD4 T cells have a reduced proliferation potential and a down-regulated expression of the apoptotic protein caspase-3." (PMID 32952832, 2020). "For chemistry indexes, there was significantly higher number of CD4+ T cells in individuals with hyperglycemia, hyperlipidemia, or combined conditions, compared with matched healthy controls." (PMID 31857499, 2019).
Hyperglycemia (continued). "To investigate the relationship between hyperglycemia and ROS production in T cells, we measured ROS levels in the CD4+CD28− T cells as well as the CD8+CD28− T cells from normal subjects and patients with prediabetes." (PMID 30867412, 2019). "In conclusion, the present study showed that persistent hyperglycemia evoked by exogenous glucose infusion for 24 hours modulates both inflammatory responses and CD4+ T cells differentiation in the MLNs, and induces the alterations of the colon microbiota." (PMID 26207186, 2015). "Mouse CD4 T-cells specific for a low-affinity insulin-derived peptide required 20 weeks before hyperglycemia developed in 50% of recipient mice." (PMID 23155466, 2012). "T2D is characterized by hyperglycemia, especially when inadequately treated, and some studies report that hyperglycemia promotes aberrant activation and higher responsiveness of peripheral CD4+ T-cells." (PMID 38794641, 2024). "Additionally, hyperglycemia impairs the ability of immune cells to migrate to infection sites and reduces phagocytic activity, making it harder for CD4 and CD8 T cells, as well as B cells, to coordinate an effective immune response." (PMID 39408710, 2024). "In diabetic patients, hyperglycemia impairs immune function by altering CD4 T cell activation." (PMID 32952832, 2020). "We guess NK and Treg were insignificantly decreased in JK5G, which may raise the possibility of combined hyperglycemia of CD4+ and CD8+T cells." (PMID 33178591, 2020). "They found that hyperglycemia was inversely correlated with live BCG-specific CD4+ T cell responses in patients with latent or active TB and that half of these diabetic patients were prescribed with glibenclamide alone in combination with other anti-diabetic drugs." (PMID 30283449, 2018). "Hyperglycaemia also affects the ability of tolerogenicDC to induce generation of antigen-specific tolerance in T cells, and there are reports that hyperglycaemiacan induce expression of proinflammatory cytokines like IL-17 in CD4+ Tcells." (PMID 28798194, 2017). "Moreover, sensitivity analyses, stratified by CD4 cell count, further confirmed the negative effect of hyperglycemia on all cause-mortality." (PMID 36301817, 2022). "However, further studies are needed to validate whether hyperglycemia progression increases the population of senescent CD4+ T cells in PBMCs." (PMID 30867412, 2019). "In the present study, we therefore hypothesized that persistent hyperglycemia for 24 hrs up-regulated the pro-inflammatory cytokines, and thereby promoted the differentiation of CD4+ lymphocytes to Th1 and Th17, which posses the ability of inducing inflammatory responses, in MLNs." (PMID 26207186, 2015). "We examined the differentiation of CD4+ lymphocytes by measuring the master genes, including the Tbx21 for Th1, the Rorc for Th17, Gata3 for Th2, and Foxp3 for Treg to evaluate whether hyperglycemia and endotoxemia synergistically modulate the balance between pro- and anti-inflammatory responses." (PMID 26207186, 2015). "Among the patients with uncontrolled DM, hyperglycemia compromises the CMI, including the activation of phagocytes, memory CD4+ and cytotoxic CD8+ T cells, and a variety of cytokines." (PMID 35270336, 2022). "The RAG2 KO, RIP-HA Tg recipients developed hyperglycemia by 8–10 days after cell transfer, whereas those receiving either CD4+ (Foxp3-GFP) +/− T-reg cells from the same F1 donors or CD4 splenic T-reg cells from Foxp3-GFP+/+ Tg parental mice did not." (PMID 22723880, 2012). "LNT was capable of stimulating the production of Treg cells from naive CD4 + T cells, which implies that LNT exhibits therapeutic values as a tolerogenic adjuvant and may be used to reverse hyperglycaemia in the early and late stages of T1D." (PMID 37031163, 2023).
Hyperglycemia (continued). "In contrast, the CAVEAT study found that NAbs and CD4 cytokine responses were lower in patients with T2DM with HbA1c levels > 7% than those with HbA1c levels ≤ 7%, implying that hyperglycemia at the time of vaccination might worsen the immunological response." (PMID 36366375, 2022). "A study in a mouse model of autoimmune colitis with high glucose uptake found that hyperglycemia did not affect intracellular CD4+ T cell metabolism." (PMID 35677051, 2022). "In the analysis of the transcriptional factors of CD4+ T lymphocytes, the interaction between endotoxemia and hyperglycemia was not statistically significant in the effect on Tbx21 or Rorc, but was in the effect on Gata3 and Foxp3." (PMID 26207186, 2015). "Autoreactive CD4 and CD8 T-cells in NOD mice infiltrate and subsequently destroy the insulin-producing beta-cells in pancreatic islets, resulting in dysregulation of blood glucose levels and hyperglycemia." (PMID 23155466, 2012). "About 72% NOD.Scid mice that were received CD4+ T cells from GAD-BPI-treated mice did not have hyperglycemia (i.e., blood glucose ≥ 250 mg/dl) after 7 weeks while only 17% of NOD.Scid mice did not have hyperglycemia when treated with CD4+ T cells from PBS-treated mice." (PMID 36381196, 2022). "Furthermore, it is unlikely that the mild hyperglycemia occurring in prediabetes could explain the phenotypic and transcriptomic changes, as well as alterations of the TCR repertoire, observed in VAT-derived CD4 Tconv cells." (PMID 38380252, 2024).
ischemic stroke (59 papers, 2011 to 2026). A stroke disorder caused by obstruction of blood flow to the brain, due to thrombotic (local blood clot formation) or embolic (due to a blood clot or other material traveling from another site) event. "There was a significant association between lower level of CD4+ count, higher levels of WC, HC, glucose, hematocrit, pulse pressure, and the presence of ischemic stroke." (PMID 22347662, 2011). "Furthermore, McMullen and colleagues found that the S41 variant is associated with lower CD4+ counts and ischemic stroke." (PMID 38395987, 2024). "However, on day 1 after ischemic stroke, transgenic mice with CD4+ or CD8+ T cells bearing a uniform TCR, mice deficient in costimulatory molecules CD28, B7-H1, or PD1 are as fully susceptible to ischemic reperfusion injury as their wild-type littermates." (PMID 34335623, 2021). "Brait VH, in 2012, states that CD4+ T cells and NK cells invade the brain 24 hr after an ischemic stroke." (PMID 40809171, 2025). "Conversely, increased levels of B cells (CD27 on IgD– CD38br and CD27 on IgD+ CD38– unswitched memory), CD4 on CD39+ CD4+ (Treg), and DN (CD4–CD8–) AC (TBNK) were linked to higher ischemic stroke risk, indicating hazardous effects." (PMID 40620597, 2025). "Following ischemic stroke, infiltration of CD4+ and CD8+ T lymphocytes into the injured brain tissue is markedly increased, with a corresponding rise in the proportion of these T cell subsets." (PMID 41451205, 2025). "Based on this, the present study investigated the effects of 25 μg estrogen (E) and 10 mg progesterone (P) per kg body weight on the inflammatory factors IL-1β and CD4+ and the infarct volume in a rat model of ischemic stroke." (PMID 40809171, 2025). "CD8+ T cells, CD4+ T cells, and NK (Natural Killer) T cells are recruited within 24 hr after the ischemic stroke, and the collection of these cells in the early inflammatory stage peaks 3 to 4 days after the injury." (PMID 40809171, 2025). "Up to one month after an ischemic stroke, there was a considerable increase in CD4+ and CD8+ T cells in the peri-infarct area." (PMID 40809171, 2025). "The MR analysis outcome revealed that CD24 on switch memory B cell (OR = 1.03, 95% CI: 1.001-1.067, p = 0.041) and CD4 on CD39+ CD4+ Treg (OR = 1.03, 95% CI: 1.002-1.054, p = 0.031) were weakly associated with an increased risk of ischemic stroke." (PMID 38562935, 2024). "T cells CD4 memory resting in cluster 5 was significantly higher in the Ischemic stroke than in the sham-operated group." (PMID 39290696, 2024). "A recent study has found that CD39 emerges as a key immunomodulatory component for neuroprotection in ischemic stroke on CD39+ activated CD4 Treg cells." (PMID 38887301, 2024). "Functioning as a histone H3 demethylase, Kdm6a has been linked to enhanced activation of female CD4 + T cell in EAE, as well as female microglial activation in ischemic stroke." (PMID 38486287, 2024). "Compared with the study of CD4+ T cells in ischemic stroke, the study of CD8+ T cells in TBI is still limited." (PMID 38077952, 2023). "Migration of CD4+ T cells and γδ T cells from the ileum to the brain was observed after ischemic stroke in photoconverted Kaede transgenic mice." (PMID 35663549, 2022). "We demonstrate the in vivo effect of rPSG1-Fc in ischaemic stroke with a clear impact on the cytokine-secreting phenotypes of CD4+ and CD8+ T cells." (PMID 36120102, 2022). "The MCAO group showed a significant decrease of CD4+ T cells in the small intestine 1 day after ischemic stroke compared to the SHAM group." (PMID 35663549, 2022). "We noticed that there was a decreased infiltration of naive CD4 T cells, CD8 T cells, resting mast cells and eosinophils and an increased infiltration of neutrophils, M0 macrophages and activated memory CD4 T cells in ischaemic stroke patients." (PMID 35962388, 2022).